IL1B (interleukin 1 beta)
Diseases named in the same sentence as IL1B in open-access papers (continued):
Sharing a sentence is not in itself a finding about the gene and the disease.
Insulin resistance (continued). "IL-1β-mediated autocrine/paracrine actions in adipose tissue that promote local inflammation and limit expandability generate a dysfunctional fat-liver communication that could contribute to liver steatosis and insulin resistance." (PMID 23341960, 2013). "Pro-inflammatory cytokines such as TNF-α, IL-1β, and MCP-1 are key mediators of adipose tissue remodeling, promoting lipogenesis, hypertrophy, and insulin resistance." (PMID 41596279, 2026). "Pro‐inflammatory macrophages, characterized by elevated expression of CD11c+ and Nos2, secrete inflammatory cytokines such as TNF‐α, IL‐6, and IL‐1β, thereby inhibiting GLUT4 expression and worsening insulin resistance." (PMID 41509193, 2026). "Specifically, IL-1β directly damages pancreatic β-cells, IL-6 affects glucose metabolism, and TNF-α plays a central role in peripheral insulin resistance." (PMID 39960958, 2025). "Pro-inflammatory cytokines IL-6, IL-1β, and TNF-α play a crucial role in MASLD-related inflammation and progression and hepatic insulin resistance." (PMID 40722894, 2025). "Persistently high levels of IL-1α and IL-1β impair insulin signaling by reducing insulin receptor substrate 1 (IRS-1) phosphorylation and disrupting its downstream pathways, leading to insulin resistance." (PMID 41087719, 2025). "A significant subset of M1-like macrophages, originating from monocytes, expresses CD11c+ and secretes pro-inflammatory cytokines such as IL-1β and TNF-α, contributing to insulin resistance." (PMID 40943464, 2025). "Understanding the roles of IL-1β, TNF-α, and hyperglycemia in the interplay between inflammation and insulin resistance opens new therapeutic avenues." (PMID 40218134, 2025). "An increased level of IL-17 activates an overabundant proinflammatory response by NF-kB signaling in adipose tissue, which results in the excessive production of IL-1β, IL-6, and TNF-α, contributing to insulin resistance." (PMID 40277935, 2025). "In visceral adipose tissue, IL-1β also mediates a pro-inflammatory loop between macrophages and CD4+ T cells via IL-22, which worsens insulin resistance and glycemic control." (PMID 40943225, 2025). "Hyperglycemia promotes elevated local levels of IL-1β, TNF-α, and MMP-9, which not only exacerbate periodontal tissue destruction but also contribute to systemic insulin resistance and β-cell apoptosis." (PMID 40283677, 2025). "Mesenchymal stem cell was found to alleviate insulin resistance in T2DM rats by suppressing NLRP3 inflammasome-mediated inflammation and expression of IL-1β and IL-18." (PMID 38987672, 2024). "This activation further triggers the production of IL-1β and TNF-α, ultimately resulting in the impairment of insulin signaling and the development of insulin resistance (IR)." (PMID 39564209, 2024). "In individuals with NAFLD, lipotoxicity, insulin resistance, and endotoxins trigger the activation of proinflammatory cytokines such as tumor necrosis factor-α (TNF-α), interleukin-1α (IL-1α), interleukin-1β (IL-1β), interleukin-6 (IL-6), and resistin." (PMID 39275255, 2024). "Further, significant decreases in IL-1β, TNF-α and ALT activities were also found in mice of the RQP group, which were inflammatory factors and play vital role in the development of insulin resistance in T2D cases." (PMID 38476942, 2024). "IL-1β decreases IRS-1tyrosine phosphorylation and its gene expression, contributing to the development of insulin resistance." (PMID 37372020, 2023). "This network is related to the following KEGG pathways (FDR less than 0.01): Insulin resistance, TNF1 and IL1B pathways, hematopoietic cell lineage and AGE–RAGE." (PMID 37365269, 2023). "The ratio of M1-like to M2-like macrophages is increased substantially resulting in copious secretion of proinflammatory mediators such as TNFα, IL-6, IL-1β, MCP-1, fetuin-A (FetA), etc. further worsening insulin resistance." (PMID 36718668, 2023).
Insulin resistance (continued). "Previous studies have shown that obese individuals have elevated IL-1β and TNF-α levels, which can induce insulin resistance, promote FFA production, and affect glucose and lipid metabolism." (PMID 37693249, 2023). "Our results suggest that IRW and IQW reduced the levels of glucose, HDL, and LDL, improved GLU tolerance and insulin resistance induced by the HF diet, and decreased the mRNA expression of TNF-α, IL-6, and IL-1β." (PMID 36232527, 2022). "Therefore, it could be speculated that apneas occurring during pregnancy, when combined with the effects of insufficient REM sleep and nocturnal hypoxia, could potentially promote insulin resistance mediated through increments in IL-1β and in plasma catecholamine concentrations." (PMID 35303833, 2022). "The dietary supplementation of RES increased the litter weight at parturition by 12.53% (p = 0.145), with ameliorated insulin resistance (HOMA-IR), increased triglyceride (TG) levels, and decreased interleukin (IL)-1β and IL-6 levels in serum (p < 0.05)." (PMID 36407549, 2022). "Herein, we show that mHypoA-2/29 neurons exposed to pro-inflammatory microglial conditioned medium (MCM) showed higher expression of the pro-inflammatory cytokines IL-6, IL-1β, and TNF-α, in addition to developing insulin resistance." (PMID 35883638, 2022). "Then, proinflammatory cytokines (IL-1β, TNF-α, and so on), and the oxidative stress response activated insulin resistance." (PMID 35457582, 2022). "Our results demonstrated that HF diet-induced insulin resistance was ameliorated by endogenous n-3 PUFAs via inhibition of HF diet-induced NLRP3 inflammasome activation and IL-1β release in adipose tissue, especially in adipose tissue preadipocytes." (PMID 36234919, 2022). "Recently, we reported that the activation of the NLRP3 inflammasome increases the IL-1β level and decreases GLUT4 translocation in adult skeletal muscle fibers in obesity-mediated insulin-resistant mice." (PMID 36552772, 2022). "TNF can induce insulin resistance and synergistically induce vascular endothelial growth factor (VEGF) production with IL1B and IL6 to affect angiogenesis." (PMID 35755045, 2022). "Recent evidence suggests a positive relationship between inflammatory markers including IL-1β, IL-6, CRP and TNF-α and insulin resistance." (PMID 34078385, 2021). "After that, the levels of glucose and insulin in serum, HOMA-IR as an indicator of insulin resistance, the ocular level of oxidative markers, TNF-α, IL-1β, MIPs, and MCP-1 along with ocular gene expression of NF-κB, Nrf2, and miR-146a-5p were evaluated." (PMID 34804425, 2021). "The development of insulin resistance and T2D has been connected with the expanded release of proinflammatory cytokines, which may impair insulin signaling, and this is supported by a clinical study in which T2D elevated FFAs and IL-1β in plasma, promoting insulin resistance." (PMID 34360006, 2021). "Another common denominator in the pathogenesis of insulin resistance, hypertension, and salt sensitivity (SS) is immune activation involving pro-inflammatory cytokines like tumor necrosis factor (TNF)-α, IL-1β, and IL-6." (PMID 34966295, 2021). "Increase levels of pro-inflammatory cytokines such as IL-1β, IL-6, TNF-α and growth hormone is an important characteristic of peripheral insulin resistance." (PMID 34416903, 2021). "In obese mice and humans, adipose tissue IL-1β and MCP-1 mRNA expression as well as their circulating levels correlated positively with insulin resistance." (PMID 33859296, 2021). "On the other hand, IL-1β and MCP-1 inhibition reduced the insulin resistance and adipose tissue inflammation in obese mice." (PMID 33859296, 2021). "The increased secretions of multiple proinflammatory cytokines and chemokines, such as IL-6, TNF-α, IL-1β, and monocyte chemoattractant protein-1 (MCP-1) in adipose tissue are involved in insulin resistance." (PMID 34043673, 2021).
Insulin resistance (continued). "Quercetin-treated female Wistar rats showed decreased levels of IL-1β, IL-6, and tumor necrosis factor (TNF)- α, and decreased insulin resistance." (PMID 32903374, 2020). "Mice fed with a high fat diet (HFD) enriched with palmitic acid display increased mRNA levels of caspase-1, NLRP3 and IL-1β in their SVF of adipose tissues, accompanied with insulin resistance and glucose intolerance." (PMID 32545355, 2020). "Levels of IL-1β, TNF-α, ROS and glucose consumption were performed to evaluate the severity of insulin resistance in FFA-induced L02 hepatocyte." (PMID 33308192, 2020). "The levels of pro-inflammatory cytokines (TNF-α, IL-1β and IL-6) and the expression of TLR4 were downregulated (P < 0.05), while the insulin resistance index, HOMA-IR showed improvement by GP treatment (P < 0.05)." (PMID 32024509, 2020). "The interaction between ox-LDL and Toll-like receptor 4 (TLR4) activates NF-κB path way resulting in elevated expression of pro-inflammatory cytokines including IL-1β, IL-6, and TNF-α which induce insulin resistance." (PMID 32005271, 2020). "The increased level of NLRP3-dependent IL-1β induces and aggravates T2DM through β cell death and insulin resistance." (PMID 32166013, 2020). "The increased production of pro-inflammatory cytokines such as “TNF- α, IL-1β, IL-6, and MCP-1” in turn, triggers chronic inflammatory reactions and enhance insulin resistance." (PMID 33329380, 2020). "The data from biochemical analysis showed that polydatin significantly decreased serum concentrations of insulin, TG, IL‐1β and TNF‐α, and alleviated insulin resistance in OGTT and ITT in fructose‐fed rats." (PMID 33058500, 2020). "For example, pro-inflammatory cytokines, including IL1β and IL17A, can induce sAT dysfunction, leading to poor lipid storage, insulin resistance and inflammation." (PMID 32599074, 2020). "Flavonoids morin, hesperidin, rutin, (rats), and chrysin (mice) were effective in reducing inflammatory cytokines IL-1β, IL-6, and TNF-α in diabetic animals, significantly improving hyperglycemia, glucose intolerance, and insulin resistance." (PMID 30764536, 2019). "Others have reported that IL-1β gene depletion in HFD obese mice attenuated adipose tissue inflammation and insulin resistance." (PMID 31200447, 2019). "Fasting plasma glucose, insulin, insulin resistance (HOMA-IR index, IRI), the S-100β protein level, and the inflammatory mediators IL-1β, IL-6 and TNF-α were assessed after surgery (postoperative day (POD) 1 and 3)." (PMID 31092210, 2019). "Macrophages begin to form so-called crown-like structures in adipose tissue and start to produce the proinflammatory cytokines involved in inflammatory responses and in insulin resistance, such as TNF-α, IL-1β and IL-6." (PMID 31363792, 2019). "AC-YVAD-CMK treatment markedly decreased caspase-1 activity, serum IL-1β, blood glucose, fasting serum insulin levels, and HOMA, an indicator of insulin resistance." (PMID 31387986, 2019). "After 6 weeks, Alanine aminotransferase (ALT), glucose, insulin, HOMA IR (Homeostatic Model Assessment for Insulin Resistance), FFA (free fatty acids), Tumor necrosis factor alpha (TNF α), IL6, IL1B levels were measured in blood." (PMID 31496048, 2019). "Visfatin-induced inflammation and insulin resistance were regulated by JAK2/STAT3 and IKK/NF-κB signaling; together with AG490 or Bay 7082, visfatin significantly reduced mRNA levels of IL-6, TNF-α and IL-1β and rescued insulin signaling." (PMID 31396538, 2019). "The activation of caspase-1 enhances the secretion of IL-1β from adipose tissue in GDM and triggers the development of insulin resistance." (PMID 31558153, 2019). "The connection between statins, NLRP3/IL-1β, and insulin resistance remains to be characterized in depth, and many mechanistic questions are still unsolved; understanding these aspects might pave the way for new therapeutic strategies, including a combination of statins and IL-1β inhibition." (PMID 31652822, 2019).
Insulin resistance (continued). "Physical activity increases the secretion of interleukin-6 (IL-6) from muscle cells, which has anti-inflammatory effects through inhibition of TNF-a and IL-1b, and reduces TNF-induced insulin resistance." (PMID 30867683, 2019). "Increased level of inflammatory cytokines, such as IFN-γ, IL-1β, IL17A, IL6, and TNF-α, is also related to insulin resistance, and increased anti-inflammatory cytokines can improve glucose metabolism which regulates insulin sensitivity." (PMID 29541033, 2018). "The relative ratios of adiponectin/TNF-α, adiponectin/IL-1β, adiponectin/IL-10, TNF-α/IL-10 and IL-1β/IL-10 have been shown to be strongly correlated with the insulin resistance/sensitivity indexes (HOMA-IR and QUICKI)." (PMID 29785210, 2018). "In this sense, prior studies suggest a positive relationship between markers of chronic inflammation, including CRP, IL-1β, IL-6, and TNF-α, and insulin resistance." (PMID 29561774, 2018). "HFB-fed mice showed signs of impaired glucose metabolism and insulin resistance along with a significant elevation in the concentration of triglycerides, LDL-cholesterol, total cholesterol, IL1β, TNF-α, IL-6, and leptin in serum." (PMID 30319558, 2018). "Activation of IL-1β, mainly through cleavage by the NLRP3 inflammasome, promotes insulin resistance." (PMID 29435463, 2017). "M1 macrophages act in the production of proinflammatory cytokines, such as IL-1β, IL-6, and TNF-α, which provoke the development of insulin resistance in adipocytes." (PMID 29077020, 2017). "Glucose-fed rats displayed hyperglycemia, hyperinsulinemia, hyperleptinemia, insulin resistance, hypertension, positive body weight gain, and enhanced expression of B1R, CPM, iNOS, and IL-1β in renal cortex, aorta and liver." (PMID 28824433, 2017). "In particular, phosphorylation of p38 MAPK is stimulated by the pro-inflammatory cytokines, TNF-α, IL-1β, and MCP-1, while activation of the JNK signaling pathway correlated with insulin resistance and pancreatic β function." (PMID 27929393, 2016). "WT and Tnfa−/− mice injected with IL-1β had similar IL-1β induction, with a greater induction of TNF-α and subsequent insulin resistance in the WT mice, demonstrating the effect of TNF-α induction by IL-1β." (PMID 27128935, 2016). "HIF-1α itself leads to activation of the pro-inflammatory cytokine, IL-1β, a well-known player in HFD-induced inflammation and insulin resistance." (PMID 27128935, 2016). "Exercise increases the secretion of interleukin-6 (IL-6) from muscle cells, which has anti-inflammatory effects through inhibition of TNF-α and IL-1β, and reduces TNF-induced insulin resistance." (PMID 27485519, 2016). "Ceramides like reconstituted low density lipoprotein ceramide 24:0 were found to increase TNF-α, IL-1β, IL-6, and MCP-1 in vitro and to induce insulin resistance in lean mice." (PMID 26788518, 2016). "Proinflammatory immune mediators, like IL-1β, IL-6, or TNF-α, are important factors in the development of insulin resistance." (PMID 27069930, 2016). "Importantly, lipid-overloaded macrophages in obese adipose tissue may trigger the production of proinflammatory cytokines such as TNFα and IL-1β, as has been observed in macrophages exposed to FAs in vitro, and thus contributing to the development of insulin resistance." (PMID 26940592, 2016). "IL-1β can negatively influence insulin signaling and subsequent glucose uptake, thereby demonstrating its role in HFD-induced insulin resistance." (PMID 27128935, 2016). "Later, other proinflammatory cytokines such as interleukin 1 beta (IL1b) and interleukin 6 (IL6) have been found to induce insulin resistance in experimental settings." (PMID 26751381, 2016). "The secreted IL-1β binds to IL-1R and activates NF-κB and MAPK pathways, thereby impairing insulin signaling through the activation of IRS-1 in adipocytes leading to insulin resistance." (PMID 26779183, 2015).
Insulin resistance (continued). "In a feed forward cycle, the ligand-RAGE signaling results in the up-regulation of RAGE along with the proinflammatory mediators, viz., IL-1β and TNF-α to promote the development of insulin resistance by disturbing insulin signaling." (PMID 25679220, 2015). "Many pro-inflammatory cytokines, such as TNF-α, IL-6 and IL-1β, have been demonstrated to be elevated in T2DM patients and participate in the development of insulin resistance." (PMID 24759263, 2014). "These large amounts of IL-1β lead to the activation of large amounts of p38-MAPK, which in turn induces insulin resistance by acting on insulin receptors, and then blocking cell differentiation." (PMID 23935446, 2013). "As cytokines released from adipose tissue lead to insulin resistance and β-cell failure, increase of TNF-α and IL-1β expression is important in the pathogenesis of type 2 diabetes." (PMID 22844333, 2012). "Parameters of liver steatosis, glutathione status, protein carbonylation, and fatty acid analysis were determined, concomitantly with insulin resistance and serum tumor necrosis factor-α (TNF-α), interleukin (IL)-1β, and IL-6 levels." (PMID 23082120, 2012). "Among them, LPS, TNF-α, IL-1β, and CD40 are involved in obesity-induced inflammation and insulin resistance suggesting a potential role for Tpl2 in this pathology." (PMID 23316186, 2012). "Increased gut permeability, promoted neutrophil infiltration, and increased levels of IL-6, IL-1β, and TNF-α, and increased skeletal muscle insulin resistance and inflammation via simulating PPAR-δ are some suggested mechanisms attributed to simple sugar intake." (PMID 39974842, 2025). "Adipose tissue-associated IL-2 is also associated with overexpression of a variety of inflammatory markers, such as IL-8, IL-12a, IL-1β, C-C motif chemokine ligand 5 (CCL5), CCL15, TLR2, and an inflammatory macrophage marker (CD11c), inducing inflammation and insulin resistance." (PMID 40863244, 2025). "Most studies reported statistically significant reductions in multiple key inflammatory mediators, particularly TNF-α, IL-6, IL-1β, and CRP, which are central to the pathophysiology of insulin resistance, adipose tissue dysfunction, and cardiovascular complications in metabolic syndrome." (PMID 40868165, 2025). "Consistent with LJ3402's suppression of circulating inflammatory cytokines (TNFα and IL‐1β), LJ3402 administration mitigated age‐related insulin resistance and impaired thermoregulation, as demonstrated by improved glucose and insulin tolerance and increased cold resistance." (PMID 41346200, 2025). "Meanwhile, it was demonstrated that mice lacking IL-1β or its receptor IL-1R1 were protected from diet-induced insulin resistance." (PMID 39940855, 2025). "Such localized inflammation impacts systemic metabolism through paracrine mechanisms; for instance, the pro-inflammatory cytokine IL-1β suppresses the expression of the thermogenic gene UCP1 in adipocytes, which reduces energy expenditure and exacerbates insulin resistance." (PMID 40568618, 2025). "Il1b is known to disrupt insulin signaling pathways by activating NF-κB and reducing insulin receptor substrate (IRS) phosphorylation, thereby contributing to systemic insulin resistance." (PMID 41019552, 2025). "Additionally, we assessed the mRNA levels of pro‐inflammatory cytokines (iNOS, TNF‐α, IL‐1β, and MCP‐1) in the adipose tissue of mice, all of which are known to contribute to insulin resistance." (PMID 39554331, 2024). "Furthermore, LrB can reduce inflammation and insulin resistance in individuals with PCOS by inhibiting NLRP3, Caspase-1, TNF-α, IL-6, IL-1β, and IL-18 and increasing the expressions of GPR120, LKB1, and AMPK." (PMID 39456928, 2024). "In obesity, the release of FFA and cytokines (IL-6, IL-1β, PAI-1, TNF-α) from VAT into the portal vein may contribute to hepatic insulin resistance, hepatic triglyceride deposition, and NAFLD—the portal hypothesis." (PMID 39063184, 2024).